AZI2 (5-azacytidine induced 2)
Description:
Adapter protein which binds TBK1 and IKBKE playing a role in antiviral innate immunity. Activates serine/threonine-protein kinase TBK1 and facilitates its oligomerization. Enhances the phosphorylation of NF-kappa-B p65 subunit RELA by TBK1. Promotes TBK1-induced as well as TNF or PMA-induced activation of NF-kappa-B. Participates in IFNB promoter activation via TICAM1.
Synonyms: Nap1; FLJ21939; AZ2; TILP
Tractability: PROTAC: UniProt records ubiquitination sites on it; ubiquitination databases record sites on it; its protein half-life has been measured; a small molecule that binds it is known.
Gene: Protein-coding gene on chromosome 3 (28,315,003 to 28,349,050, reverse strand). Ensembl gene ENSG00000163512.
Subcellular location: Cytoplasm
Gene Ontology:
Molecular function: protein binding
Biological process: defense response to virus; type I interferon-mediated signaling pathway; negative regulation of canonical NF-kappaB signal transduction
Cellular component: cytoplasm; serine/threonine protein kinase complex
Genetic constraint (gnomAD): Loss-of-function variants: 15 observed, 33.72 expected, observed/expected ratio (o/e) 0.44, 90% interval 0.3 to 0.69. The upper end of that interval is the gene's LOEUF score, 0.69, which puts it in group 2 of 6, group 1 being the genes least tolerant of losing a copy. Missense variants: 371 observed, 397.81 expected, observed/expected ratio (o/e) 0.93, 90% interval 0.86 to 1.02. Synonymous variants: 121 observed, 141.66 expected, observed/expected ratio (o/e) 0.85, 90% interval 0.74 to 0.99.
Homologues: Orthologues: chimpanzee AZI2 (100% identical), macaque AZI2 (98% identical), dog AZI2 (91% identical), guinea pig AZI2 (90% identical), pig AZI2 (86% identical), mouse Azi2 (84% identical), rat Azi2 (81% identical), tropical clawed frog azi2 (42% identical), zebrafish azi2 (32% identical). Paralogues in human: TBKBP1 (28% identical).
Diseases named in the same sentence as AZI2 in open-access papers:
AZI2 is named in the same sentence as 7 diseases in open-access papers, as found by Europe PMC text mining. Sharing a sentence is not in itself a finding about the gene and the disease. The quoted sentences say what the papers report.
breast carcinoma (3 papers, 2021 to 2024). "By inhibiting RB1CC1, AZI2 accumulates, leading to overactivation of TBK1-IFN, promotion of cytokine expression in breast cancer, CD8T cell infiltration, and improvement of the response of breast cancer to ICI." (PMID 39161768, 2024). "Five proteins (LMAN1, AZI2, STAU2, MMP9 and PLOD1) from a systemic analysis of a variety of array data of breast cancer patients were subjected to immunofluorescence staining to evaluate the presence of fixed WBCs on 96-well plates from 363 healthy females and 358 female breast cancer patients." (PMID 33441653, 2021).
dermatitis (1 paper, 2024). An inflammatory process affecting the skin. "Tank/Azi2/Tnfrsf1aTKO mice did not experience the delayed hair growth observed at four weeks of age in Tank/Azi2DKO animals and did not develop dermatitis by 30 weeks of age." (PMID 39562788, 2024).
osteoporosis (1 paper, 2024). A condition of reduced bone mass, with decreased cortical thickness and a decrease in the number and size of the trabeculae of cancellous bone (but normal chemical composition), resulting in increased fracture incidence. "Although AZI2 knockout mice develop severe osteoporosis due to enhanced osteoclast survival, no mitophagy-related phenotypes associated with AZI2 deficiency have been reported in vivo." (PMID 39276928, 2024).
Sepsis (1 paper, 2024). Sepsis is defined as life-threatening organ dysfunction caused by a dysregulated host response to infection. "The Venn diagram shows that a total of eight overlapping genes were discovered between ACSL4 co-expression genes and sepsis, including GK, CLEC4E, ACSL1, TGFBR3, ADAM9, AZI2, BCAT1, and CYP1B1." (PMID 39262873, 2024).
infection (5 papers, 2017 to 2023). The state of being infected such as from the introduction of a foreign agent such as serum, vaccine, antigenic substance or organism. "Similarly, the mRNA expression of the MAVS and AZI2 was also elevated during most of the post-infection periods, except 24-, 120-, and 144 hpi." (PMID 36119061, 2022). "Moreover, during infection, genes involved in the regulation of the NF-κB cascade (AZI2, TBK1 and NFKBIA) and NFKB1were transcriptionally unaltered in all the respiratory tract of alpacas may be preventing acute inflammation in response to MERS-CoV." (PMID 34029358, 2021).
AZI2 also shares sentences with these, for which no sentence is quoted: autoimmune disease (1 paper); melanoma (1).